PF4V1 (platelet factor 4 variant 1)
Description:
Inhibitor of angiogenesis. Inhibitor of endothelial cell chemotaxis (in vitro).
Synonyms: CXCL4V1; SCYB4V1; CXCL4L1; PF4-ALT; PF4A
Tractability: Antibody: UniProt places it where antibodies can reach, with medium confidence; UniProt predicts a signal peptide or a membrane-spanning region; its Gene Ontology location is reachable by antibodies, with medium confidence.
Gene: Protein-coding gene on chromosome 4 (73,853,296 to 73,854,483, forward strand). Ensembl gene ENSG00000109272.
Subcellular location: Secreted
Pathways (Reactome):
Hemostasis: Cell surface interactions at the vascular wall; Regulation of clotting cascade
Gene Ontology:
Molecular function: protein binding; chemokine activity; CXCR chemokine receptor binding
Biological process: antimicrobial humoral immune response mediated by antimicrobial peptide; cellular response to lipopolysaccharide; inflammatory response; neutrophil chemotaxis; chemotaxis; defense response; immune response
Cellular component: extracellular region
Genetic constraint (gnomAD): Loss-of-function variants: 5 observed, 7.79 expected, observed/expected ratio (o/e) 0.64, 90% interval 0.33 to 1.34. That is too few expected variants to judge how well the gene tolerates losing a copy. Missense variants: 127 observed, 133.55 expected, observed/expected ratio (o/e) 0.95, 90% interval 0.82 to 1.1. Synonymous variants: 68 observed, 58.3 expected, observed/expected ratio (o/e) 1.17, 90% interval 0.96 to 1.43.
Homologues: Orthologues: chimpanzee PF4V1 (94% identical), macaque PF4V1 (87% identical). Paralogues in human: PF4 (84% identical), PPBP (40% identical), CXCL1 (36% identical), CXCL5 (36% identical), CXCL6 (35% identical), CXCL2 (33% identical), CXCL3 (31% identical), CXCL8 (26% identical), CXCL10 (24% identical), CXCL13 (24% identical), CXCL9 (23% identical), CXCL11 (20% identical).
Diseases named in the same sentence as PF4V1 in open-access papers:
PF4V1 is named in the same sentence as 40 diseases in open-access papers, as found by Europe PMC text mining. Sharing a sentence is not in itself a finding about the gene and the disease. The quoted sentences say what the papers report.
diabetes (2 papers, 2019 to 2025). "PF4V1 also preserves the integrity of the blood-retinal barrier in diabetes patients." (PMID 40294019, 2025). "Furthermore, studies on other disease targets, such as the role of the translocator protein (TSPO) in glioblastoma and the potential role of GPR35 in diabetes and hypertension, provide valuable references for understanding the mechanism of action of PF4V1 in NMOSD." (PMID 40294019, 2025).
endometrial cancer (2 papers, 2022 to 2025). Primary or metastatic malignant neoplasm involving the endometrium (mucous membrane that lines the endometrial cavity). "Quantification analysis in 36 patients with endometrial cancer compared to 36 healthy individuals confirmed the upregulation of APOA1, HBB, CA1, HBD, LPA, SAA4, PF4V1, and APOE." (PMID 36551747, 2022).
lymph node metastases (2 papers, 2020 to 2021). "Another study identified four proteins (platelet factor 4 variant 1, C-X-C motif chemokine, cDNA FLJ93141, and apolipoprotein A-1) that may be related to the metastasis of oral squamous cell carcinoma, and it was suggested that they may be helpful for the diagnosis of lymph node metastases." (PMID 34571828, 2021). "Combined with qPCR-based validation findings from tissue, serum and whole blood samples, they highlighted that serum exosomal proteins, PF4V1, CXCL7, F13A1 and ApoA1 may be related to the OSCC lymph node metastasis." (PMID 32054041, 2020).
amyloidosis (1 paper, 2025). A disorder characterized by the localized or diffuse accumulation of amyloid protein in various anatomic sites. "In the SMC-calc vs. SMC comparison based on limma, clusters related to high-density lipoprotein (HDL) assembly (PF4V1, APOA1, LPXN, AFP, A2M, and MMP1) and amyloidosis (CX3CL1, APOE, PLIN3, TGFBI, and CH25H) were identified." (PMID 41301179, 2025).
COVID-19 (1 paper, 2024). A disease caused by infection with severe acute respiratory syndrome coronavirus 2. "PF4V1, decreased in our COVID-19 patients, is an angiogenesis inhibitor and may also regulate inflammation and thrombosis." (PMID 38760690, 2024). "Thus, the decreased expression of IGFBP-5, PF4V1, and SeprinA4 in COVID-19 may be cardioprotective, perhaps via suppression of angiogenesis and vascular transformation." (PMID 38760690, 2024).
dengue (1 paper, 2017). "PF4V1/CXCL4L1, a variant of PF4/CXCL4, was found to be down-regulated in platelets from dengue patients compared to control." (PMID 28542641, 2017).
Nasu-Hakola disease (1 paper, 2025). "Levels of inflammatory factors are increased in patients with Nasu-Hakola disease, while PF4V1 expression is significantly decreased, underscoring its anti-inflammatory role." (PMID 40294019, 2025).
oral cancers (1 paper, 2021). "In keeping with this concept, we and others report reduced expression of platelet factor 4 variant 1 in oral cancers with nodal disease, and speculate that its downregulation is a deliberate mechanism adopted by OTSCC to facilitate nodal metastases." (PMID 34571828, 2021).
platelet disorders (1 paper, 2023). "PF4V1 is involved in platelet disorders and clot formation; interaction with the coagulation system was long suggested to play a role in SOS." (PMID 37018234, 2023).
prostate carcinoma (1 paper, 2022). A carcinoma that arises from epithelial cells of the prostate gland. "It is known that PF4V1 in prostate cancer leads to suppression of proliferation and invasion, and serves as a potential prognostic biomarker." (PMID 36551747, 2022).
Sepsis (1 paper, 2023). Sepsis is defined as life-threatening organ dysfunction caused by a dysregulated host response to infection. "sepsis was associated with the C11_Plate cluster, and ESAM, HBG2, MMRN1, PF4V1, SAMD14, SELP, and TGFB1I1 may be important in this context." (PMID 37919720, 2023).
thymoma (1 paper, 2015). A neoplasm arising from the epithelial cells of the thymus. "In MG patients with versus without thymoma, 58 lncRNAs had 271 ‘cis’ genes upstream or downstream of their chromosomal position: lncRNA oebiotech_22652 had the highest number of ‘cis’ genes, whereas lncRNA oebiotech_12244 had 6 ‘cis’ genes(PPBP, CXCL1, CXCL5, PF4V1, PF4, and C14orf45)." (PMID 25889429, 2015).
ZIKV infections (1 paper, 2021). "Three of the differentially expressed proteins, i.e., Fibrinogen Alpha, Platelet Factor 4 Variant 1, and Pro-Platelet Basic Protein, predicted Zika virus infection at a ∼70% true-positive and 6% false-positive rate." (PMID 33582300, 2021). "Further, we used a machine learning approach to distinguish between the DENV and ZIKV infections based on protein expression profiles of the 13 differentially proteins and a subset of three proteins (FGA, PF4V1, PPBP)." (PMID 33582300, 2021).
tumor (16 papers, 2014 to 2025). "Pre-clinical studies have shown that platelet factor 4 variant 1 can prevent nodal metastases by inhibiting tumor lymphangiogenesis, cell migration, tumor growth, and angiogenesis." (PMID 34571828, 2021). "In addition, deregulated tumor tissue gene expression of Platelet factor 4 variant 1 has been reported previously." (PMID 34571828, 2021). "Thus, an adeno-associated vector with fibstatin and platelet factor-4 variant 1 (CXCL4L1) genes has inhibited angiogenesis, lymphangiogenesis and tumor spread to the lymph nodes in vivo." (PMID 31698727, 2019). "Then, we performed a literature review and found that PF4V1 has already been validated as miR-875-3p target, which was also dysregulated in several tumor diseases." (PMID 35062989, 2022). "Also, PF4V1 exhibits potent anti-angiogenic properties, effectively inhibiting tumor growth." (PMID 40294019, 2025). "The anti-tumoral activity of PF4V1 via inhibition of angiogenesis and induction of apoptosis within tumor tissue was confirmed by the significant downregulation of this gene expression in tumor tissue of Western populations (log2-fold change: −3.20; adjusted P < 0.05)." (PMID 27857161, 2016). "WB analysis of serum and tumor tissue specimens confirmed the upregulation of eight proteins: APOA1, HBB, CAH1, HBD, LPA, SAA4, PF4V1, and APOE." (PMID 39194522, 2024). "PF4V1 also known as CXCL4L1, displays a strong anti-angiogenic function and thus impairs tumor growth." (PMID 27857161, 2016). "PF4V1, also known as CXCL4L1, is involved in angiogenesis, inflammation, and tumor." (PMID 40294019, 2025).
cancer (8 papers, 2014 to 2022). A tumor composed of atypical neoplastic, often pleomorphic cells that invade other tissues. "PF4V1 suppresses chemokine angiogenesis by blocking the protein bFGF, and is closely associated with the growth and metastasis of various cancers." (PMID 36551747, 2022). "PF4V1, also known as CXCL4L1, suppresses cell proliferation, migration, and invasion in various cancer by targeting ERK1 and AKT." (PMID 35062989, 2022). "Among them, a gradual increase from early-stage cancer to more advanced stages were strongest for APOC2 and IL8 genes followed by for SAA4 and OSM genes, whereas HIST1H1E, PF4V1, CXCL5, and IL2RA expression showed limited stage-wise upregulation." (PMID 33828156, 2021).
neurodegenerative disease (1 paper, 2013). A disorder of the central nervous system characterized by gradual and progressive loss of neural tissue and neurologic function. "PF4 and its variant form (PF4V1) are involved in numerous biological processes including inflammation and angiogenesis; two processes implicated in neurodegenerative disease such as ALS." (PMID 24224000, 2013).
PF4V1 also shares sentences with these, for which no sentence is quoted: melanoma (5 papers); atherosclerosis (2); Coronary Artery Disease (2); endometriosis (2); lung carcinoma (2); acute coronary syndrome (1); breast carcinoma (1); breast tumor (1); cardiovascular disease (1); colon cancer (1); dementia (1); esophageal cancer (1); glioblastoma (1); heart disease (1); Hypertension (1); infection (1); liver fibrosis (1); myocardial infarction (1); oral squamous cell carcinoma (1); osteosarcoma (1); ovarian carcinoma (1); pancreatic cancer (1); rheumatoid arthritis (1); Stroke (1).